ATRX (ATRX chromatin remodeler)
Diseases named in the same sentence as ATRX in open-access papers (continued):
Sharing a sentence is not in itself a finding about the gene and the disease.
cervical cancer (3 papers, 2021 to 2023). A primary or metastatic malignant neoplasm involving the cervix. "Additionally, survival analysis on cervical carcinoma suggested that the loss-of-function of ATRX was associated with a better prognosis in patients treated with chemo-radiation." (PMID 38126976, 2023).
epithelioid sarcoma (3 papers, 2021 to 2025). An aggressive malignant neoplasm of uncertain differentiation, characterized by the presence of epithelioid cells forming nodular patterns. "Nevertheless, mutations in regulators of the epigenome have also been described in MFSs, for example ATRX, a member of the SWI/SNF family of chromatin remodeling proteins, which is a potential explanation for clustering near epithelioid sarcoma." (PMID 38791144, 2024).
Fanconi anemia (3 papers, 2018 to 2024). Fanconi anemia (FA) is a hereditary DNA repair disorder characterized by progressive pancytopenia with bone marrow failure, variable congenital malformations and predisposition to develop hematological or solid tumors. "Genes that were upregulated by the presence of R-loops in HPV positive cells included those in the DNA damage repair such as ATM, ATRX, and members of the Fanconi Anemia pathway." (PMID 39178326, 2024). "Our studies show that genes like ATM, ATRX, RAD51C, along with members of the Fanconi Anemia pathway (FANC-B, C, E, I, L, and M), and SETD2, the methyltransferase regulating H3K36me3, were all associated with the combination of H3K36me3, γH2AX and enhanced R-loops." (PMID 39178326, 2024).
HCMV infection (3 papers, 2022 to 2024). "In total, we conclude that ATRX acts in an antiviral mode at the start of productive HCMV infections to repress viral transcription but in a pro-viral manner at later times to better equate viral genome production with capsid packaging limits." (PMID 39236084, 2024). "Perhaps more importantly, our work reveals a later, positive role for ATRX during HCMV infection." (PMID 39236084, 2024). "Thus, Daxx may be allowed to re-accumulate during HCMV infection to permit the Daxx-ATRX complex to slow viral DNA replication, allowing for efficient viral genome packaging." (PMID 39236084, 2024). "The impact of PML-NBs on lytic HCMV infection has been characterized by numerous studies in primary human fibroblasts, which revealed an inhibitory effect of the main NB components PML, Sp100, Daxx and ATRX on viral immediate–early (IE) gene expression." (PMID 36233232, 2022). "Lastly, but perhaps most intriguingly, the ability of ATRX to increase the expression of cellular genes downstream of innate immune activation independent of Daxx during HCMV infection may impact viral DNA replication." (PMID 39236084, 2024). "Since several interaction partners of Daxx, including ATRX, have been shown to bind in a mutually exclusive manner, the absence of ATRX from PML cages may indicate an altered regulation of Daxx during HCMV infection that leads to a switch of interaction partners." (PMID 35319461, 2022).
hepatic angiosarcomas (3 papers, 2021 to 2025).
herpesvirus infection (3 papers, 2011 to 2024). "Taken together, our data demonstrate an important role of BNRF1 in supporting EBV early infection by interacting with Daxx and ATRX; and suggest that tegument disruption of PML-NB-associated antiviral resistances is a universal requirement for herpesvirus infection in the nucleus." (PMID 22102817, 2011).
lymphoma (3 papers, 2019 to 2022). A malignant (clonal) proliferation of B- lymphocytes or T- lymphocytes which involves the lymph nodes, bone marrow and/or extranodal sites.
ovarian carcinoma (3 papers, 2020 to 2023). A malignant neoplasm originating from the surface ovarian epithelium. "Recurrently mutated ovarian cancer driver genes, including LRP1B, KMT2A, ARID1A, KMT2C and ATRX were also found in two cell lines." (PMID 37525498, 2023).
PEComas (3 papers, 2024 to 2025).
pituitary carcinomas (3 papers, 2022 to 2025). A primary or metastatic malignant neoplasm affecting the pituitary gland. "Loss of ATRX expression was also noted in 27% of the 26 pituitary carcinomas presented across the studies included in this review." (PMID 40440300, 2025). "Of the 26 pituitary carcinomas included in the review, 7/26 (27%) exhibited a loss of ATRX expression." (PMID 40440300, 2025). "The elevated prevalence of ATRX mutations among pituitary carcinomas supports the proposed association between ATRX loss and increased propensity for aggressive and proliferative development of tumours." (PMID 40440300, 2025). "Furthermore, tumours lacking ATRX expression exhibit increased proliferative or transformative characteristics, including a higher incidence of ATRX loss in pituitary carcinomas." (PMID 40440300, 2025). "It is also important to note that in one excluded study, a pituitary carcinoma was found to exhibit ATRX mutations and expression loss in a liver metastasis but not in the original tumour, highlighting the potential for pituitary carcinomas to gain ATRX mutations." (PMID 40440300, 2025).
thyroid cancer (3 papers, 2019 to 2023). "In thyroid carcinoma, some subtypes harbor mutations of SWI/SNF subunits, including ATRX, and the frequency of abnormal SWI/SNF complex is lower." (PMID 36245994, 2022). "Conversely, ALT mechanisms as determined by mutations in ATRX and DAXX, are not reported in non-medullary cells derived thyroid cancers in many different studies, thus an involvement of these mechanisms in telomere deregulation may be likely excluded in this pathogenic environment." (PMID 31200515, 2019).
uveal melanoma (3 papers, 2022 to 2024). A melanoma derived from melanocytes of the uveal tract. "Similar to TERT promoter mutations, ATRX loss is very rare in uveal melanoma, which is another ocular melanoma." (PMID 37629169, 2023). "The American Association for Cancer Research recently reported an ATRX loss-of-function mutation in one uveal melanoma in their cancer registry." (PMID 35365243, 2022).
ACTHomas (2 papers, 2020 to 2025). "The proportion of ACTH-secreting tumours (corticotroph adenomas and corticotrophic pituitary carcinomas) exhibiting loss of ATRX expression was significantly different from the proportion of other tumours that exhibited ATRX loss (p < 0.0005)." (PMID 40440300, 2025). "Additionally, whole exome sequencing (WES) analysis revealed several other mutations associated with ACTHomas, including those in the NR3C1, DAXX, ATRX, and HCFC1 genes." (PMID 33266265, 2020).
adenoma (2 papers, 2017 to 2021). A neoplasm arising from the epithelium. "The same conclusion was recently reached also for sporadic PanNET: aberrant MEN1 expression was observed in 74% of micro-adenomas; in contrast, none of these micro-adenomas display the alternative lengthening of telomeres phenotype and do not display DAXX and ATRX loss." (PMID 29156578, 2017).
Anxiety (2 papers, 2025 to 2026). Intense feelings of nervousness, tension, or panic often arise in response to interpersonal stresses. "In the light-dark paradigm, ATRX miKO mice spend significantly more time in the lit area compared to control mice, suggesting reduced anxiety levels." (PMID 40938932, 2025). "Several anxiety tests were conducted, revealing noteworthy differences between the ATRX miKO and control groups." (PMID 40938932, 2025). "Behavioral analyses revealed that T29-1 CaMKIIα-Cre ATRX knockout mice exhibited significant hypoactivity and increased anxiety traits, particularly in the open field, but retained normal hippocampal-dependent contextual fear memory and spatial learning and memory." (PMID 42048321, 2026). "In summary, behavioral testing shows that mice lacking ATRX in microglia exhibit lower anxiety levels and impaired long-term spatial memory." (PMID 40938932, 2025).
chondrosarcoma (2 papers, 2017 to 2024). A malignant cartilaginous matrix-producing mesenchymal neoplasm arising from the bone and soft tissue. "Two out of 36 chondrosarcomas (5.6%) show complete loss of ATRX." (PMID 28484589, 2017). "Genomic profiling has revealed telomerase reverse transcriptase (TERT) gene amplification and ATRX mutations, in addition to TERT promoter mutations, in approximately 20% of high-grade chondrosarcomas and DDCSs." (PMID 38275833, 2024). "Two out of 36 (5.6%) conventional chondrosarcomas in the first cohort for which staining was evaluable show complete loss of ATRX (data not shown)." (PMID 28484589, 2017).
ductal adenocarcinoma (2 papers, 2021 to 2025). "However, the most common molecular alterations found in ductal adenocarcinoma (KRAS), cystic neoplasms (GNAS and RNF43), and NENs (MEN1, DAXX, and ATRX) are rarely found in ACC." (PMID 41120769, 2025).
dwarfism (2 papers, 2009 to 2013). "Loss-of-function mutations in the human ATRX gene are associated with skeletal defects and high incidence of dwarfism." (PMID 24386478, 2013). "Mutations in the human ATRX gene cause developmental defects, including skeletal deformities and dwarfism." (PMID 19774083, 2009).
fibrosarcoma (2 papers, 2019 to 2025). A malignant mesenchymal fibroblastic neoplasm affecting the soft tissue and bone. "To determine if the relationship between ATRX and PML expression is causal, we depleted ATRX in HT1080 fibrosarcoma cells using siRNA treatment and examined PML protein expression." (PMID 30745338, 2019).
giant cell glioblastoma (2 papers, 2020 to 2023).
meningioma (2 papers, 2017 to 2021). A generally slow growing tumor attached to the dura mater. "The low prevalence of the loss of ATRX suggests that this alternative mechanism of telomere elongation is a rare phenomenon in malignant meningiomas." (PMID 34573966, 2021). "It is possible that other known cancer-specific mechanisms of telomere maintenance such as ATRX/DAXX mutations or TERT rearrangements could be present in meningiomas." (PMID 29312603, 2017). "In addition, we performed ATRX immunohistochemistry from meningiomas in our cohort at different stages during progression (n= 42)." (PMID 29312603, 2017). "In malignant meningiomas, all tumour cells retained nuclear ATRX expression; likewise, non-tumour cells such as ECs, microglia/macrophages, reactive astrocytes, and lymphocytes." (PMID 34573966, 2021). "Together with a recent report of no loss of ATRX or DAXX expression by IHC in 58 grade II and III meningiomas, these results provide evidence that the ALT pathway is not a frequent mechanism for telomere maintenance in progressive higher-grade meningiomas." (PMID 29312603, 2017).
microcytic anemia (2 papers, 2024 to 2025). Anemia in which the red blood cell volume is decreased. "Loss of ATRX function is related to reduced alpha-globin transcription and mild microcytic anemia." (PMID 40896065, 2025).
non-small cell lung carcinoma (2 papers, 2014 to 2017). A group of at least three distinct histological types of lung cancer, including non-small cell squamous cell carcinoma, adenocarcinoma, and large cell carcinoma. "In H1299 cells miR-200c targets multiple non-small cell lung cancer prognostic markers DLC1, ATRX, and HFE." (PMID 24997798, 2014). "An increase in ATRX foci also is seen in A549 and H1975 non-small-cell lung cancer cell lines that undergo CDK4i-induced senescence but not in H358 in which CDK4i induces quiescence." (PMID 28855512, 2017).
pituitary neoplasm (2 papers, 2022).
Rett syndrome (2 papers, 2014 to 2017). A severe neurodevelopmental disorder affecting the central nervous system.
uterine sarcoma (2 papers, 2020 to 2025).
Adrenal insufficiency (1 paper, 2013). Insufficient production of steroid hormones (primarily cortisol) by the adrenal glands. "Complete sex reversal in 46,XY males without adrenal insufficiency can also occur in conditions such as Leydig cell hypoplasia or due to mutations in SRY, DHH, SOX9, DMRT1, WNT1, or ATRX." (PMID 23748066, 2013).
anaplastic oligoastrocytoma (1 paper, 2019). An oligoastrocytoma characterized by the presence of increased cellularity, nuclear atypia, pleomorphism, and high mitotic activity. "One case was left as anaplastic oligoastrocytomas since it had both 1p/19q loss and ATRX mutation." (PMID 30592195, 2019).
aneuploidy (1 paper, 2010). Chromosomal disorder consisting of the presence a chromosomal abnormality in which there is an addition or loss of chromosomes within a set. "At this stage, ATRX deficient oocytes (n = 82) also exhibit a high incidence of aneuploidy (59.7%) compared with only 7.4% observed in controls (n = 66; P<0.001)." (PMID 20885787, 2010).
benign smooth muscle tumors (1 paper, 2025).
Bladder Cancer (1 paper, 2025). "In our cohort, DAXX and ATRX expression exhibited distinct patterns in prostate and urinary bladder cancers." (PMID 41472189, 2025).
bladder tumours (1 paper, 2025). "Our findings provide a better understanding of how DAXX and ATRX expression is altered in canine prostate and bladder tumours, indicating that their potential clinical relevance should be further investigated." (PMID 41472189, 2025).
brainstem gliomas (1 paper, 2020).
breast NETs (1 paper, 2022). "Furthermore, typical pathogenetic or unknown variants of PNETs and other NENs, such as ATRX, DAXX and MEN1, were very rarely detected in breast NETs." (PMID 36085291, 2022). "Similarly with MEN1, these pathogenetic or unknown variants were still very rare in breast NETs: none of the samples harboured ATRX pathogenetic or unknown variants, and only one patient had a DAXX pathogenetic or unknown variants." (PMID 36085291, 2022).
Burkitt lymphoma (1 paper, 2011). A rare form of malignant mature B-cell non-Hodgkin lymphoma. "To explore the role of Daxx and ATRX in the context of EBV latent to lytic gene regulation, we test the effects of Daxx and ATRX knockdown on viral lytic gene expression in Mutu I cells, an EBV-latently infected Burkitt's lymphoma cell line." (PMID 22102817, 2011).
campomelic dysplasia (1 paper, 2022). "All children had established syndromes (eg, X-linked lissencephaly/ATRX, campomelic dysplasia/SOX9, Scimitar syndrome), chromosomal deletions or complex multisystem involvement, often associated with fetal growth restriction." (PMID 36419940, 2022).
esophageal cancer (1 paper, 2019). A primary or metastatic malignant neoplasm involving the esophagus. "As far as we know, only a study performed on human esophageal cancer cells has highlighted an IR-dependent modulation of ATRX shortly after irradiation." (PMID 31336873, 2019).
hypercortisolism (1 paper, 2021). "ATRX was highly expressed (median score of 3.08) in the non-hypercortisolism group, and it showed a low expression (median score of 0.5) in the hypercortisolism group." (PMID 33513905, 2021). "Although all of them presented with hypercortisolism at initial presentation and died due to ACC (OS 7, 36, and 12 months, respectively), they presented with variable expression of ATRX (score 2, 0, and 0, respectively) and variable expression of ZNRF3 (score 3, 2, and 5, respectively)." (PMID 33513905, 2021).
intestinal neuroendocrine tumors (1 paper, 2023). "These events are not observed in intestinal neuroendocrine tumors and, accordingly, the organoid culture showed prominent nuclear expression of both ATRX and DAXX." (PMID 37082125, 2023).
Jacobsen syndrome (1 paper, 2019). A multiple congenital anomaly/intellectual disability contiguous gene syndrome caused by partial deletion of the long arm of chromosome 11. "Compromised ATRX function is the underlying cause of a rare neurodevelopmental syndrome (Alpha thalassemia retarded X-linked), a phenotype also typical of other disorders associated with increased fragile site stability, including Jacobsen syndrome (increased FRA11B breakage)." (PMID 31180492, 2019).
Knee osteoarthritis (1 paper, 2013). "Knee osteoarthritis scores were slightly higher, with control animals having an averaged maximal score of 1.46 for any quadrant of frontal knee sections and ATRX-deficient animals having a score of 0.67." (PMID 24386478, 2013). "Similar to other models of ATRX loss in the skeleton, AtrxPrx1 mice do not demonstrate knee osteoarthritis, with a maximal OA score of 2.18 in mutant knees and 1.78 in control littermates (p=0.69)." (PMID 24386478, 2013).
lentivirus infection (1 paper, 2022). Virus diseases caused by the Lentivirus genus. "Importantly, replication among the clones was not affected after the lentivirus infection and the GFP-ATRX KO clones showed increased levels of γH2AX as compared to their tdTomato-ATRX WT counterparts, as seen for the unlabeled clones used for the initial screen." (PMID 35406561, 2022).
liver cancer (1 paper, 2017). An epithelial or non-epithelial malignant neoplasm that arises from the liver. "and cancer driver genes (ATRX, MDC1, RIF1, APC and PCM1) showed a phosphorylation related signal transition network affecting cell proliferation ability and revealed the extreme complex nature of phosphoproteome transformation in liver cancer cells." (PMID 28883432, 2017).
Lynch syndrome (1 paper, 2022). An autosomal dominant hereditary neoplastic syndrome characterized by the development of colorectal carcinoma and a high risk of developing endometrial carcinoma, gastric carcinoma, ovarian carcinoma, renal pelvis carcinoma, and small intestinal carcinoma.